FAM237A (family with sequence similarity 237 member A)
Description:
May activate the G protein-coupled receptor GPR83. Has orexigenic activity (By similarity).
Gene: Protein-coding gene on chromosome 2 (206,642,417 to 206,649,365, forward strand). Ensembl gene ENSG00000235118.
Subcellular location: Secreted
Gene Ontology:
Biological process: regulation of feeding behavior
Cellular component: extracellular region
Genetic constraint (gnomAD): Loss-of-function variants: 18 observed, 15.29 expected, observed/expected ratio (o/e) 1.18, 90% interval 0.81 to 1.72. The upper end of that interval is the gene's LOEUF score, 1.72, which puts it in group 6 of 6, group 1 being the genes least tolerant of losing a copy. Missense variants: 240 observed, 214.23 expected, observed/expected ratio (o/e) 1.12, 90% interval 1.01 to 1.25. Synonymous variants: 85 observed, 78.3 expected, observed/expected ratio (o/e) 1.09, 90% interval 0.91 to 1.3.
Homologues: Orthologues: chimpanzee FAM237A (99% identical), macaque FAM237A (96% identical), dog FAM237A (86% identical), pig FAM237A (83% identical), mouse Fam237a (78% identical), rat Fam237a (75% identical). Paralogues in human: FAM237B (22% identical).